TSLP (thymic stromal lymphopoietin)
Diseases named in the same sentence as TSLP in open-access papers (continued):
Sharing a sentence is not in itself a finding about the gene and the disease.
asthma (continued). "Furthermore, Th2 high subgroup analyses revealed that serum TSLP level was uniquely associated with the asthma stage." (PMID 40503233, 2025). "In such a study, increased production of IL-33 and TSLP was linked to increased asthma severity." (PMID 40869013, 2025). "Additionally, the angiogenetic events underlying airway vascular remodeling in asthma are significantly affected by TSLP." (PMID 41321706, 2025). "Tezepelumab’s broad anti-inflammatory effects, due to TSLP targeting, may offer potential benefits in obese individuals with severe asthma by addressing underlying inflammation and improving asthma control, even in the absence of specific biomarkers." (PMID 40649123, 2025). "Analyzing additional SNPs in STAT6 (e.g., rs324015, rs3024944, rs71802646) and other genes (e.g., IL1RL1, GATA3, ADAM33, TSLP, FOXO3a) would expand the scope of genetic analysis and provide a comprehensive understanding of asthma susceptibility in the population." (PMID 40375219, 2025). "Furthermore, multivariate logistic regression analysis confirmed TSLP’s independent association with asthma remission (OR=1.009, P=0.023), adjusting for confounders." (PMID 40503233, 2025). "These lower IL‐13 levels may also be associated with lower TSLP levels in males with asthma compared with females." (PMID 40022441, 2025). "The question is whether asthma risk is modified by the combined effects of TSLP and IL-33 genotypes and whether it is correlated with atopy." (PMID 38731070, 2024). "Furthermore, we provide evidence for an association between ER stress and TSLP expression in clinical bronchial biopsies from severe asthma patients, in particular those with neutrophilic inflammation." (PMID 38469627, 2024). "An asthma-associated long form of TSLP is produced by epithelial cells following viral infection." (PMID 38453256, 2024). "In previous studies, associations between various TSLP SNPs and asthma were analyzed." (PMID 38731070, 2024). "Besides allergic diseases in the airway such as asthma, aberrant TSLP activity has been linked to allergic diseases of the skin and gut, including atopic dermatitis, allergic rhinitis, and food allergy." (PMID 39726595, 2024). "Given the emerging roles of TSLP and periostin as diagnostic markers in conditions like asthma and obstructive lung disease, it is anticipated that I3C may exert multifaceted therapeutic effects against various diseases, including allergic skin inflammation." (PMID 39722037, 2024). "In addition, TSLP contributes to the occurrence and development of various types of diseases, such as asthma, variant dermatitis, inflammatory bowel disease, and breast cancer." (PMID 39703503, 2024). "Similarly, SNP in the TSLP gene promoter was associated with the expression of this cytokine gene in asthma, increased IgE levels and eosinophilia." (PMID 38731070, 2024). "Therefore, we attempted to analyze an extensive and up-to-date study concerning TSLP polymorphism and asthma." (PMID 39118763, 2024). "In an attempt to understand the genetic influence of TSLP on asthma, this meta-analysis was designed to understand the genetic influence of TSLP on asthma and estimate the association between a single nucleotide polymorphism and the risk of developing asthma." (PMID 39118763, 2024). "The study suggests that the rs1837253 polymorphism may be involved in the regulation of TSLP secretion and could help explain the protective association of this genetic variant with asthma and related traits." (PMID 38672419, 2024). "Regarding the medium-term respiratory morbidity, the detection of nasal TSLP was significantly associated with the prescription of maintenance asthma treatment (p = 0.04), prescription of montelukast (p = 0.01), and the combination montelukast plus inhaled glucocorticosteroids (IGC) (p = 0.03)." (PMID 36694181, 2023).
asthma (continued). "The overexpression of TSLP can result in pathologic inflammation pathways driving various inflammatory phenotypes such as allergic, eosinophilic, neutrophilic and paucigranulocytic, which cause symptoms and asthma exacerbations." (PMID 37628907, 2023). "TSLP, an epithelial-derived cytokine similar to IL-17, is known to induce deregulation of Th2 responses and increase the expression of chemokines that attract Th2 cells, a hallmark feature of allergic inflammatory diseases such as AR and asthma." (PMID 37648989, 2023). "Thymic stromal lymphopoietin (TSLP), a cytokine released from epithelial cells, is believed to trigger a number of cell groups and inflammatory pathways implicated in the pathophysiology of asthma." (PMID 36463281, 2022). "This may include biomarkers, endotypes, and phenotypes to select best candidates for the emergent TSLP-driven asthma therapies addressing the precise underlying airway pathogenesis and lung immunobiology." (PMID 36245744, 2022). "Our prior studies have shown that TSLP is the primary type 2 airway epithelial response of human infants during viral infections, which is highly relevant as early-life viral infections predispose to subsequent asthma development later in life." (PMID 36245744, 2022). "With genome-wide association studies demonstrating associations between single-nucleotide polymorphisms of the TSLP and IL-33 gene and risk of asthma, it will be important to understand which subsets of asthma patients will benefit most from anti-alarmin therapy." (PMID 35406669, 2022). "Interestingly, eosinophil extracellular trap induction by TSLP is associated with the severity of asthma and promotes this through pulmonary neuroendocrine cells via the CCDC25-ILK-PKCα-CRTC1 pathway." (PMID 36311787, 2022). "Polymorphisms in the TSLP gene have been associated with asthma." (PMID 35572064, 2022). "The suppression of TSLP is expected to reduce the risk of asthma exacerbations." (PMID 35269440, 2022). "Our findings suggested that TSLP-induced ROS production and mitophagy in monocytes-macrophages may be associated with pulmonary fibrosis in asthma." (PMID 35292112, 2022). "Moreover, in addition to airway epithelial cells, airway smooth muscle cells adjacent to mast cells (as well as mast cells themselves) release TSLP thereby implementing paracrine and autocrine loops implicated in asthma pathobiology." (PMID 33922072, 2021). "In the present study, we found that TSLP per se is an independent factor for predicting future risk of asthma exacerbation, and serum TSLP levels ≥ 25 pg/mL are associated with a high probability of asthma exacerbation (AOR = 8.19)." (PMID 33875671, 2021). "TSLP and tryptase levels may be implicated in steroid resistance and responsiveness in the asthma inflammatory process." (PMID 33875671, 2021). "Higher ATP levels are associated with elevated IL-25 and TSLP expression in type 2–high asthma." (PMID 33945508, 2021). "Indeed, TSLP gene variants have been associated with lower lung function in healthy individuals as well as a susceptibility locus to asthma." (PMID 34418598, 2021). "Furthermore, interesting studies based on genome-wide association strategies have shown that some single-nucleotide polymorphisms (SNPs) detected within the TSLP gene are coupled with the relevant asthma risk." (PMID 34572294, 2021). "However, TSLPR expression on basophils is minimally associated with asthma severity, indicating a limited role for basophils in TSLP-induced inflammation." (PMID 34249003, 2021). "Previous studies have shown TSLP to be a methylation-sensitive gene, and hypomethylation at its promoter was associated with atopic dermatitis and prenatal tobacco smoke exposure, two asthma-associated features." (PMID 34629083, 2021). "Increased TSLP expression, caused by decreased TSLP methylation level, has been linked to the occurrence and exacerbation of atopic diseases such as atopic dermatitis, asthma, and allergic rhinoconjunctivitis." (PMID 33836808, 2021).
asthma (continued). "TSLP potentially played the pathogenic role across different asthma phenotypes." (PMID 33875671, 2021). "Our study proposed that the combined biomarkers of serum TSLP and tryptase levels, and blood eosinophil count may be linked to distinct inflammatory mechanisms in asthma and be useful to predict the future risk of asthma exacerbation." (PMID 33875671, 2021). "Thymic stromal lymphopoietin (TSLP), a key alarmin in asthma pathogenesis, initiates Th2 responses that promote allergic airway inflammation and are implicated in contributing to corticosteroid insensitivity in asthma." (PMID 34572965, 2021). "TSLP and tryptase levels may be implicated in steroid resistance/responsiveness in the asthma inflammatory process." (PMID 33875671, 2021). "This association led to the development of anti-TSLP agents to treat TH2-asthma." (PMID 33673725, 2021). "Epithelium-derived cytokines, including TSLP and IL-33, have a pivotal role in the development of allergic response at gut barrier surface and have been linked to the pathogenesis of type 2 inflammatory diseases, including food allergy and asthma." (PMID 33679694, 2020). "Studies have shown that TSLP encodes a hemopoietic cytokine and promotes T helper type 2 cells responses, which are linked to immune response in various inflammatory diseases, including asthma, allergic inflammation and chronic obstructive pulmonary disease." (PMID 32413869, 2020). "TSLP appears to be also implicated in T2-low asthma pathobiology." (PMID 33329598, 2020). "For example, whole blood QTLs related to genes known to affect asthma pathogenesis or severity (e.g. IL18R, ZFP57, BTN3A2, NDFIP1, SMAD3, CLEC16A, and TSLP) were associated with colocalization sites for asthma and neutrophil, eosinophil, monocyte and/or lymphocyte traits." (PMID 32600345, 2020). "Inhibition of TSLP causes marked declines in several biomarkers, including blood eosinophils, serum immunoglobulin E (IgE), and fractional exhaled nitric oxide (FeNO), and has ripple effects on multiple downstream inflammation cascades involved in asthma." (PMID 32120846, 2020). "One study found significant correlations between genetic variants of TSLP and asthma." (PMID 31290290, 2019). "In human bronchial epithelial cells, TSLP expression is associated with asthma severity." (PMID 31612365, 2019). "Similarly, studies investigating genetic polymorphisms in the TSLP gene have reported specific single nucleotide polymorphisms (SNPs) to be linked with asthma, atopic dermatitis (AD) and allergic rhinitis (AR)." (PMID 31768185, 2019). "Furthermore, a recent study indicated TSLP as a strong susceptibility gene for asthma among adult Japanese populations." (PMID 31290290, 2019). "Several genetic analyses have linked TSLP to Th2-polarized immunity and asthma." (PMID 31355170, 2019). "TSLP is a signature “Th2-favoring” or proallergic cytokine that has recently been linked to asthma." (PMID 29670037, 2018). "Recognition of the powerful effects of IL-25, IL-33, and TSLP produced by respiratory epithelial cells is an important new element in understanding the potential for respiratory viruses to cause and/or exacerbate asthma." (PMID 29915592, 2018). "Additionally, polymorphisms in the TSLP gene are associated with both childhood atopic and adult asthma, possibly via higher TSLP production in response to viral respiratory infections." (PMID 30386455, 2018). "We sought to explore the plasma levels of biomarkers associated with asthma (periostin, TSLP and YKL-40), COPD (NGAL) and their possible correlation with lung function, the bronchodilator response and radiographic imaging in patients with asthma, COPD and with features of ACO." (PMID 29580282, 2018). "Thymic stromal lymphopoietin (TSLP) is associated with several allergic diseases including asthma." (PMID 29343779, 2018).
asthma (continued). "TSLP-influenced pulmonary Treg function is associated with tolerogenic immunity and increased protein expression in bronchoalveolar lavage fluids in the airways of patients with asthma." (PMID 29670037, 2018). "Association studies demonstrate a relationship between asthma and TSLP." (PMID 31826038, 2018). "Additionally, TSLP SNPs that result in increased TSLP activity are associated with increased susceptibility to asthma." (PMID 28959799, 2017). "Monoclonal antibodies have also been developed to another type 2 cytokine, thymic stromal lymphopoietin (TSLP), which was implicated in asthma using genome-wide association studies (GWAS), and these TSLP monoclonal antibodies were recently tested in a clinical trial." (PMID 29202803, 2017). "Finally, we will highlight the benefits of using biologics to treat asthma-associated allergic airway inflammation with an emphasis on the potential of targeting cytokine alarmins, especially thymic stromal lymphopoietin." (PMID 27378934, 2016). "TSLP has been found to be overexpressed in patients with asthma, atopic dermatitis, and food allergies, and specific polymorphic variants have been found to be associated with asthma and airway hyper-responsiveness." (PMID 27378934, 2016). "Genetic variants of TSLP have been associated with AD and asthma and high levels of epidermal TSLP precede the clinical presentation of childhood AD, suggesting that TSLP may be particularly important in the establishment of AD." (PMID 27453775, 2016). "In humans, TSLP is implicated in the pathogenesis of both atopic dermatitis and asthma." (PMID 24843010, 2014). "We reasoned that although ORMDL3 levels may not affect the production of IL-6 or IL-8 cytokines, perhaps they were impacting gene expression of other important immune genes, such as IL-33, IL-25 and TSLP, which have all been implicated in asthma pathogenesis." (PMID 23369242, 2013). "To determine whether TSLP is the underlying trigger of airway remodeling in chronic allergen-induced asthma, we induced allergic airway inflammation in mice by intranasal administration of house dust mite (HDM) extracts for up to 5 consecutive weeks." (PMID 23300949, 2013). "Indeed, several studies in humans and mouse models have implicated TSLP in the development and progression of allergic diseases, including atopic dermatitis, asthma and AR." (PMID 22973903, 2012). "Studies of endobronchial biopsy specimens and BAL fluid of subjects with severe asthma have shown that asthma is associated with elevated bronchial mucosal expression of TSLP and Th1-attracting (IP-10/CXCL10) and Th2-attracting (TARC/CCL17, MDC/CCL22) chemokines." (PMID 22523502, 2012). "Since asthma is prevalent in urban communities, variants in the TSLP gene may be important in asthma susceptibility in these populations." (PMID 21966427, 2011). "TSLP SNP rs1837253 is associated with reduced odds for AR in boys with asthma." (PMID 21244681, 2011). "Genetic variants in TSLP may contribute to asthma susceptibility in admixed urban populations with a gene and environment interaction." (PMID 21966427, 2011). "Because of the importance of TSLP as a target for environmental-associated asthma, we examined the association of genetic variants of TSLP with asthma in an admixed urban community using genetic ancestral informative markers to control for population substructure." (PMID 21966427, 2011). "The risk for asthma was associated with a specific haplotype of TSLP involving SNP rs1898671." (PMID 21966427, 2011). "Haplotype analysis of TSLP also revealed an elevated risk of asthma associated with one haplotype." (PMID 21966427, 2011). "In summary, these data suggest that genetic variants in TSLP may influence asthma risk in complex populations with an environmental interaction." (PMID 21966427, 2011). "Previous studies have shown that TSLP is associated with AD and asthma in humans and mice." (PMID 20064775, 2010).
asthma (continued). "TSLP, a general biomarker for skin-barrier defects, is an interleukin-7 (IL-7)–like cytokine produced by epithelial cells and is implicated in the pathogenesis of both AD and asthma." (PMID 19557146, 2009). "Although we showed that TSLP signaling is necessary for the development of asthma in RBP-j–deficient animals with chronic allergic skin inflammation, it remains unclear whether other factors associated with AD-like skin lesions contribute to this atopic march." (PMID 19557146, 2009). "In the context of asthma, rhinoviral infection may also exacerbate airway remodeling through induction of cup cell metaplasia, increased mucus production and activation of signaling pathways associated with type 2 responses (e.g., IL-33, TSLP)." (PMID 40746413, 2025). "Spearman’s correlation coefficients were conducted to investigate whether serum TSLP level has associations with subjects’ clinical characteristics in Th2-high asthma and whether it can be used as a predictor to evaluate the ongoing eosinophilic inflammation remission." (PMID 40503233, 2025). "We sought to assess whether the upper airway epithelium of patients with asthma may be an alternative source for the measurement of intracellular alarmin cytokines (TSLP, IL-25, and IL-33) in asthma and whether their expression is altered in association with asthma severity." (PMID 38999286, 2024). "Furthermore, TSLP polymorphism also increased the risk of asthma in children with AD." (PMID 37628907, 2023). "The main goal of this study was to evaluate whether there is some association between the nasal detection and the levels of TSLP and periostin, in infants admitted for bronchiolitis, and the subsequent development of recurrent wheezing and asthma at 4 years of age." (PMID 36694181, 2023). "Thus, among epithelial-derived cytokines, IL-33 and TSLP might contribute to ILC2-associated asthma." (PMID 37371472, 2023). "TSLP polymorphism may also be related to allergic disease and eosinophilia in patients with asthma." (PMID 35626330, 2022). "In addition, TSLP was found to be significantly associated with Japanese adult asthma patients." (PMID 32397396, 2020). "Therefore, blocking TSLP in patients with OCS-dependent asthma may potentially reverse corticosteroid insensitivity caused by TSLP, permitting reductions in OCS dose or cessation of OCS treatment." (PMID 33050928, 2020). "However, this was a brief observation study for 4 weeks to minimize the risk of exacerbations and course variability of asthma that could have an impact on TSLP and IL-25 production." (PMID 31885750, 2019). "This suggests that early-life RSV-infection in males leads to persistent TSLP-associated Th2/Th17 immune-driven pathology within the lungs, while the same early-life infection in females allows for appropriate Th2/Th17 resolution thereby protecting females from later asthma pathogenesis." (PMID 31076663, 2019). "Additionally, TSLP has been implicated in the pathogenesis of asthma." (PMID 31076663, 2019). "Collectively, DSG1 contributed crucially to bronchial barrier integrity, and HDM could induce long-term deficiency of DSG1 and abnormal expression of TSLP which might result in a sensitive microenvironment at bronchial epithelium, and lead to asthma relapse upon another allergen exposure." (PMID 32076408, 2019). "Viral infections that trigger TSLP secretion may increase the risk of asthma." (PMID 29670037, 2018). "Furthermore, interrogating how other cytokine combinations that are frequently associated with the asthma phenotype (e.g. IL-13, IL-4, TSLP) may reveal novel mechanisms for regulating XDH expression and uric acid production." (PMID 28863172, 2017). "We have previously reported that TSLP gene variants, as a potential susceptibility locus to asthma, was associated with lower lung function in healthy individuals, which is also in line with the contention that genetic determinants of lung function influence susceptibility to asthma." (PMID 26752288, 2016).